IL17A (interleukin 17A)
Diseases named in the same sentence as IL17A in open-access papers (continued):
Sharing a sentence is not in itself a finding about the gene and the disease.
colitis (continued). "ACKR2 expression in colitis mucosa prevents migration of IL-17A-secreting Tγδ cells to this microenvironment, leading to exacerbation of colitis in mice." (PMID 35677043, 2022). "In mice supplemented with 50:50 CLA, IL-17A was elevated in mesenteric lymph nodes and the spleen in a colitis model." (PMID 36544518, 2022). "Our data suggest that pretreatment with Rg1 and ADSC + Rg1 markedly decreases the levels of TLR4 and MyD88, as well as the expression of TNF-α, IL-6, IL-1β, IFN-γ, and IL-17A in the DSS-induced mouse model of colitis." (PMID 35729638, 2022). "IL-17A has been shown to have protective effects on DSS-induced colitis by showing antimicrobial properties, activating neutrophil recruitment, enhancing intestinal epithelial integrity, and inducing cytoprotective prostaglandins." (PMID 35677043, 2022). "In particular, studies examining mouse and human colonic tissue have reported on IL-17A+ CD4+ T cell or IFNγ+IL-17A+ CD4+ T cell populations that has been shown to exacerbate colitis severity." (PMID 36704549, 2022). "Together, these data indicate that following mucosal injury, TAGAP deficiency was associated with increased IL-17A-producing and IFN-γ-producing CD4+ T cells infiltration and proinflammatory gene expression, which greatly exacerbated colitis severity." (PMID 36704549, 2022). "During the induction of colitis, IL-17A expression was notably increased in CD69+CD103− CD4+ TRM cells." (PMID 35844584, 2022). "Our study found a significant increase in colonic expression of IL-17A, as well as IFNγ and IL-2, during colitis in mPGES-1−/− mice compared with WT mice." (PMID 34983695, 2022). "To verify the effect of egg treatment on Th17 function in the colitis mice, next we detected IL-17A concentration in serum and splenocyte supernatant from all groups." (PMID 36304936, 2022). "IL-17A expression in CD69+CD103− CD4+ TRM cells was impaired in TIGIT−/− mice during the induction of colitis." (PMID 35844584, 2022). "CD69+CD103− CD4+ TRM cells are the major source of IL-17A production in the gut of mice with DSS-induced colitis." (PMID 35844584, 2022). "In the large intestinal lamina propria (LILP) of T-cell-specific Rap1-knockout mice (Rap1KO mice), Th17 cells were found to increase in a microbiota-dependent manner, and the inhibition of IL-17A production prevented the development of colitis." (PMID 35246619, 2022). "In rats, butyrate administration ameliorates colitis by increasing numbers of regulatory T cell (Treg) and suppressing levels of the pro-inflammatory cytokine IL-17A in both plasma and colonic mucosa." (PMID 35371048, 2022). "During DSS-induced colitis, IL-17A+IFN-γ+CD4+ T cell levels were significantly reduced after MNS treatment." (PMID 35784693, 2022). "In our study, PAMK treatment significantly decreased the frequency of Th17 cells in the spleen and MLN, and the expression of Il17a in colonic tissue in colitis mice." (PMID 36341374, 2022). "Quantitative analysis showed that the proinflammatory factors secreted by Th1/Th2/Th17, including IL-2, IL-6, TNF-α, IFN-γ and IL-17A significantly increased in the colitis group in both their serum and colonic tissues." (PMID 35372817, 2022). "In our in vivo adoptive transfer colitis experiment we observed a decrease not only in IL-17a+ cells but also in IL-17a− IFNγ+ cells." (PMID 35835905, 2022). "Taken these results together, the ndSTAT1-TMD treatment also showed therapeutic efficacy in DSS-induced colitis comparable to anti-IL-17A antibody treatment." (PMID 36591260, 2022). "Whereas IL-23-independent IL-17A production by innate(-like) immune cells is considered to be protective in colitis by maintaining barrier function in the intestines, IL-23-dependent IL-17A production by Th17 cells results in gut inflammation." (PMID 34267743, 2021).
colitis (continued). "In the colons of patients and mice with colitis, Th17 responses are much stronger than those in heathy controls, while the frequencies of Th17 cells together with the levels of IL-17A in the lungs and BALFs of mice with asthma are also up-regulated 41-44." (PMID 33754076, 2021). "Consistently, DSS-induced colitis rats exhibited upregulation of IL-17A and IL-6 and downregulation of IL-10 and TGF-β1 in the colonic tissues." (PMID 33722292, 2021). "Animal colitis models suggest that exaggerated ILC3 activation worsen experimental colitis through the secretion of IL-17A and IL-22 and subsequent excess neutrophil influx resulting in tissue damage." (PMID 34118489, 2021). "The dextran sulfate sodium (DSS)-induced colitis mouse model showed exacerbated inflammation after IL-17A neutralization." (PMID 33924897, 2021). "Cytokines related to colitis pathology (such as IL-6, IL-1β, IFNγ, and IL-17a) are significantly inhibited in the colon tissue of exosome-treated model mice." (PMID 34683937, 2021). "For example, in an adoptive transfer model of colitis, transferring CD4+CD25- T cells from RORγt-/- mice to RAG-1-/- immunodeficient mice is unable to induce colitis, while treatment with IL-17A can restore colitis after the transfer of RORγt-/- T cells." (PMID 33754076, 2021). "A study in experimental colitis provided evidence that inhibition of both IL-17A and IL-17F was necessary to attenuate colitis." (PMID 34267743, 2021). "IL-17A can exist as a homodimer, or it can pair with IL-17F to form a heterodimer, both of which are present in the colon of hapten-induced colitis mice." (PMID 33553436, 2021). "The infection elevates TGF-β but lowers the IL-17A, IL-17F, IL-6, IL-21, and IL-23 levels, thus likely affecting the immunosuppressive Treg balance across the colon environment in the colitis model." (PMID 33924897, 2021). "In particular, Th1 (producing IFN-γ), Th17 (producing IL-17A and IL-17F) and Treg (producing IL-10) have been reported to be associated with Crohn’s Disease in humans and DSS-induced colitis in mice." (PMID 34407839, 2021). "Studies in the dextran-sulfate sodium (DSS)-induced colitis model revealed that IL17F deficiency leads to colitis reduction, whereas IL17A deficiency resulted in a more severe course of the disease." (PMID 33859636, 2021). "In an anti-CD4 and anti-CD90 antibody-depleting mouse colitis model, IL-6 was found to contribute to the activation and production of IL-17A, IL-22 and IFN-γ in intestinal ILC3s, a finding confirmed in isolated lamina propria cells from IBD patients." (PMID 34299236, 2021). "IL-17A and IL-17F have been established as the central pro-inflammatory cytokines in colitis, though a controversy regarding IL-17A is noted." (PMID 33871822, 2021). "IL-17A played a pivotal part in the development of dextran sodium sulfate-induced colitis by regulating the balance of Th17 and Treg cells." (PMID 34646877, 2021). "Recently, other members of the DOK family of proteins, namely DOK1 and DOK2, have been shown to regulate colitis severity through inhibiting the expression of Th17 cytokines IL17A and IL22 in DOK1/2 double knockout mice." (PMID 34743196, 2021). "For example, Ogawa et al51 reported that the neutralization of IL‐17A aggravates DSS‐induced colitis in mice." (PMID 33300279, 2021). "It was shown that the neutralization of IL17A in a dextran sodium sulfate (DSS) murine colitis model resulted in elevated tissue damage and T cells, lacking IL17A or IL17R, transferred into RAG-1 deficient mice, led to increased severity of the colitis course." (PMID 33859636, 2021). "In mice, IL-17A or IL-17 receptor deficient T cells induce flare of colitis when transferred into RAG-1 deficient mice, and blocking IL-17A increases tissue damage and leads to enhanced inflammation." (PMID 34539646, 2021).
colitis (continued). "ET treated mice had less severe colitis as evidenced by reduced weight loss, colonic inflammation, and production of inflammatory cytokines (TNF-α, IFN-γ, and IL-17A) from the colon." (PMID 33717186, 2021). "We have observed enhanced expression of these mediators in our colitis model and have previously demonstrated that inhibition of these TLRs decreases IL-17A production in response to EBV DNA." (PMID 34210024, 2021). "We noted that, administration of S-EVs into the ileal loop of DSS-colitis mice significantly suppressed the mucosal inflammation-associated increase in TNF-α and IL-17A compared to that of control EVs (C-EVs)." (PMID 33182773, 2020). "Further experimental validation revealed that CSCC attenuated DSS-induced colitis by the suppression of the mRNA levels of IL-17A and of the cytokines it induces, such as IL-6, IL-1β, and TNF-α." (PMID 32382313, 2020). "We have shown a decreased expression of IL-17A in the colorectum during colitis, while a significantly up-regulated IL-17F level adversely aggravated epithelial injury and hastened ArgmyeKO mice death eventually." (PMID 32391010, 2020). "Only small populations of RORγt+ cells were observed in the acute colitis model (both WT and Il17a−/− mice [1.1% and 2.0%, respectively])." (PMID 31941937, 2020). "Collectively, these results demonstrated an attenuated protection in the intestines of ArgmyeKO mice due to decreased IL-17A level during colitis." (PMID 32391010, 2020). "IL-17A is a potent enhancer of DSS-induced colitis phenotype, with elevated IL-17A secreted by Th17 cells promoting secretion of IL-12 and IL-23, and triggering a conversion of the response from Th17 to Th141,42." (PMID 32444671, 2020). "This anti-inflammatory cytokine is important in suppressing IFN-γ and TNF-α by limiting macrophage activity, the production of which in mice was shown to be promoted by Bacteroides fragilis to inhibit colitis through the suppression of IL-17a production." (PMID 32670220, 2020). "Together, these results suggested that Arg-1 deletion attenuates a protective role of MDSC during colitis by dichotomously regulating IL-17A and IL-17F levels in the colorectum, thus contributed to the exacerbation of colitis." (PMID 32391010, 2020). "SSP and 5-ASA significantly reduced IL-1β, IL-4, IL-9, and IL-17A concentrations in the colitis mice, followed by lower expression of the CD11c+CD103+E-cadherin+ and CD11c+CD103+TNF-α+ cells." (PMID 32754049, 2020). "An anti-IL-17A antibody, secukinumab, was also used to inhibit IL-17A function in the colitis model." (PMID 31941937, 2020). "Anti-IL-17A therapy can attenuate acute colitis because IL-17A is a potent inducer of neutrophil-promoting cytokines." (PMID 31941937, 2020). "We also detected an increased IL-23 in the colorectum of ArgmyeKO mice during colitis, which was critical for IL-17A signal activation." (PMID 32391010, 2020). "These components acted to protect mice against colitis inflammation by significantly suppressing cytokines [γ‐interferon (IFNγ), IL‐6,IL‐1β, and IL‐17a] related to colitis pathology and upregulating anti‐inflammatory cytokine IL‐10." (PMID 32410383, 2020). "IL-17A has been proposed to promote the maintenance of intestinal epithelial cell integrity based on observations that IL-17A inhibition exacerbates colitis in a mouse model, which leads to weakening of the intestinal epithelial barrier." (PMID 31937680, 2020). "High level of Arg-1 favors accumulation of IL-17A, but reduced IL-17F expression in the colorectum of mice and ultimately leading to relief of colitis, indicating a potential clinical impact of MDSC-derived Arg-1 for controlling inflammatory bowel disease." (PMID 32391010, 2020). "One study proposed that IL-17A plays suppressive roles in spontaneous colitis in conjunction with IL-10 through myeloid derived suppressor cell (MDSC) and inducible nitric oxide synthase (iNOS)." (PMID 32676080, 2020).
colitis (continued). "IL-17A expression by NCR− ILC3s has been demonstrated to drive colitis development in T-bet−/−.Rag2−/− (TRUC) mice." (PMID 33193381, 2020). "And IL-17A is regard as a main product of Tfh17 cells, so high-expressed IL-17A in colitis mice hinted that elevated level of Tfh17 cells is possible phenomenon in the pathogenesis of colitis." (PMID 32581849, 2020). "IL‐17f, an IL‐17a heterodimer partner, is a prime mediator of colitis, and we showed a significant reduction in this cytokine expression levels in FKK6‐treated mice compared to vehicle‐treated mice." (PMID 32153125, 2020). "IL-23A-responsive ILCs were also found to mediate intestinal pathology in a murine colitis model, and IL-1β-responsive IL-17A-producing ILCs have been reported in the conjunctiva." (PMID 31964744, 2020). "The validation study using anti-IL-17A antibody showed similar results to the DSS-induced colitis model in Il17a−/− mice." (PMID 31941937, 2020). "Given the opposite roles of IL-17A and IL-17F in colitis, we next evaluated genes regulated by IL-17 A/F." (PMID 32391010, 2020). "In contrast, IL-17A-deficient mice with severe colitis presented milder intestinal inflammation and decreased M2-like macrophages, suggesting a potential beneficial effect of IL-17A in colitis." (PMID 32987705, 2020). "Protection against C. rodentium is known to require IL-17a and IL-17f, however, IL-17f-deficient mice are resistant to dextran sodium sulfate (DSS)-induced colitis, presenting milder acute intestinal inflammation." (PMID 32082288, 2020). "Subsequently, acute and chronic colitis mouse models were validated using the IL-17A inhibitor secukinumab." (PMID 31941937, 2020). "In mice, IL-23 driven inflammatory IL-17A and IL-6 are essential for T-cell-mediated colitis and blockade of IL-23 with monoclonal antibodies inhibits these responses." (PMID 31906479, 2020). "The results showed that IL-17A mRNA expression was reduced, whereas that of IL-17F was abnormally increased in the colorectums of ArgmyeKO mice, indicating an opposite functions of IL-17A and IL-17F during colitis." (PMID 32391010, 2020). "As with the previously reported effect of melatonin on DSS- or TNBS-induced colitis, melatonin suppresses potent pro-inflammatory mediators in colitis such as Il1b and Il17a, and controls microbiota in the intestine." (PMID 32042047, 2020). "A few studies have demonstrated that the blocking of Th17 derived IL-17A increased the dextran sodium sulfate (DSS)-colitis symptoms (a protective meaning), and IL-17F deficiency relieved the symptoms of colitis (a proinflammatory meaning)." (PMID 32630805, 2020). "The Sears group showed that IL-17A neutralization by antibodies induces suppression of ETBF-induced colitis, strongly implying that ETBF-induced inflammation is dependent on IL-17." (PMID 33126615, 2020). "Collectively, MDSC-derived Arg-1 promotes IL-17A expression in the colorectum, inhibits IL-17F expression and greatly relives colitis in mice." (PMID 32391010, 2020). "Our data showed that high level of IL-17A production, often associated with TH17 cells in PP and mLN, obviously relieve weight loss of mice with colitis." (PMID 32391010, 2020). "High level of Arg-1 facilitates TH17 cell polarization and enhances IL-17A expression but inhibits IL-17F level in the colorectum during colitis." (PMID 32391010, 2020). "XylB treatments reversed the imbalance between pro- (IL-1β, TNF-α, and IL-17A) and anti-inflammatory (IL-10) cytokines in experimental colitis." (PMID 32429359, 2020). "In contrast, IL-17F knockout mice are reported to be protected against chemically induced colitis, whereas IL-17A knockout mice remain sensitive." (PMID 31937680, 2020). "Adoptive transfer of IL-17A-, IL-17F-, or IL-22-deficient T lymphocytes into RAG1-null mice results in more severe colitis than that caused by wild-type T cells." (PMID 30804707, 2019).
colitis (continued). "In summary, our findings show that M2b macrophage exosomes attenuate disease activity, up-regulate Treg cells and IL-4, and reduce pro-inflammatory cytokine (IL-1β, IL-6, and IL-17A) production in mice with DSS-induced colitis." (PMID 31749791, 2019). "Here, using mouse models of colitis, we demonstrate that loss of intestinal-epithelial RANK and NIK is associated with a decrease in the expression of pro-inflammatory IL17A in the intestinal LF." (PMID 30737385, 2019). "The addition of AICAR resulted in the suppression of the frequency of IFN-γ- and IL17A-producing colitis LP CD4+ T cells." (PMID 31417110, 2019). "Our results showed that IL-1β, IL-6, and IL-17A were all down-regulated in mice with DSS-induced colitis, following treatment with M2b macrophage exosomes." (PMID 31749791, 2019). "Exposure to even low doses of Al (1.5 mg/kg) has been shown to aggravate intestinal damage in mouse colitis models, such as worsening of colitis and upregulation of the mRNA expression of inflammatory cytokines IL1β, IL17A, and Nlrp3." (PMID 31523502, 2019). "We measured IFN-γ- and IL-17A-producing colitis LP CD4+ T cells using AMPK agonist, 5-Aminoimidazole-4-carboxamide ribonucleotide (AICAR) and antagonist, Compound C (C.C.)." (PMID 31417110, 2019). "IL-17A levels respond similarly, showing a clear upregulation after disease induction, supporting the Th17 axis in the experimental murine colitis model." (PMID 31238939, 2019). "Administration of Dab2-deficient DCs (DC2.4Dab2−/− cells) modulated the course of DSS colitis in wild-type mice, enhanced mucosal expression of Tnfa, Il6, and Il17a, and promoted neutrophil recruitment." (PMID 30873168, 2019). "The mucosa of CD patients, as well as in mice with adoptive T cell transfer colitis, is infiltrated by a mix of IL-17A+ and IFN-γ+ T cells." (PMID 30873168, 2019). "In contrast, other studies have suggested that IL-17A has a protective role in a T-cell transfer model of colitis." (PMID 29849501, 2018). "On the other hand, protective effects of IL17A were ascribed to an IL17A-mediated attenuation of T-bet and IFNγ expression, leading to a more aggressive colitis upon transfer of IL17A−/− CD4 T cells into lymphopenic hosts." (PMID 29416538, 2018). "On the other hand, there are studies reporting a protective effect of IL-17A in various colitis models, such as dextran sulfate sodium (DSS)-induced or T cell-mediated colitis models." (PMID 29124320, 2018). "Recently, also IL-17A derived from group 3 innate lymphoid cells (ILC) in response to IL-23 has been shown to mediate intestinal inflammation in an innate colitis model." (PMID 29124320, 2018). "We provide evidence that F. hepatica EVs can prevent DSS-induced colitis by down regulating pro-inflammatory cytokines like TNFα, IL-6, and IL17A, as well as suppressing MAPK/NF-κB signaling pathways." (PMID 29875750, 2018). "On one hand, disease promoting effects in mouse models of colitis were ascribed to IL17A/F-mediated signaling as blocking IL17A and IL17F ameliorated disease." (PMID 29416538, 2018). "In a recent study, IL-23-treated neutrophils produced IL-17A selectively, and IL-17+ neutrophils were found in the colons of a DSS-induced colitis model through the adoptive transfer of IL-23-treated neutrophils." (PMID 30013577, 2018). "SHP2 deficiency in T cells aggravated colitis with increased level of pro-inflammatory cytokines including IFN-γ and IL-17A." (PMID 27935860, 2017). "Continuous CD40-signalling disables CD103+ DCs to induce RORγt+Foxp3+ iTreg cells and causes accumulation of IL-17A+IFN-γ+ Th17/Th1 T cells, breakdown of tolerance to gut microbiota, dysbiosis and fatal colitis." (PMID 28276457, 2017). "The observed clinical and histopathological improvement of colitis upon EPO or cibinetide treatment was also associated with reduced levels of nitrite, TNF, IL-1ß, IL-6, IL-12p70, IL-23, IFN-γ and IL-17A in supernatants of colonic organ cultures." (PMID 29026145, 2017).